CYP27B1 (cytochrome P450 family 27 subfamily B member 1)
Diseases named in the same sentence as CYP27B1 in open-access papers (continued):
Sharing a sentence is not in itself a finding about the gene and the disease.
preeclampsia (4 papers, 2014 to 2022). Preeclampsia is a hypertensive disorder of pregnancy that is characterized by new-onset hypertension with proteinuria presenting after 20 weeks of gestation, and depending on mild or severe forms may initially present with severe headache, visual disturbances, and hyperreflexia. "Single‐nucleotide polymorphisms (SNPs) were genotyped 50 kilobases up‐ and down‐stream in three genes (VDR,GC, and CYP27B1) in the samples from both studies, for a total of 744 preeclampsia cases and 2411 controls." (PMID 29380949, 2018). "In contrast, in whole human placental tissues, the expression of CYP27B1 mRNA and protein have been found higher in preeclampsia." (PMID 26247971, 2015). "Few studies show decreased CYP27B1 expression in cultured syncytiothrophoblasts of preeclampsia placentas compared to controls, and increased CYP27B1 protein levels in freshly obtained placentas from preeclamptic pregnancies compared to healthy pregnancies." (PMID 25148115, 2014). "Indeed, when CYP27B1 has been studied in syncytiotrophoblast cells in culture, our laboratory has demonstrated low gene expression and activity of this enzyme in preeclampsia." (PMID 26247971, 2015). "It is possible that CYP27B1 gene expression is differentially regulated across gestational age and that the time point chosen in our sampling protocol was not one during which aberrant expression levels between patients with preeclampsia and controls were present." (PMID 25148115, 2014). "We assessed the expression of CYP27B1, an activator of calcidiol, and Vitamin D receptor (VDR) in placentae from NW and OB, and women with gestational diabetes and preeclampsia." (PMID 35712242, 2022). "In a subgroup, mRNA expression of CYP24A1 (24-hydroxylase), CYP27B1 (1α-hydroxylase) and VDR (vitamin D receptor) were quantified by real time PCR in placental samples of 14 women with normal pregnancies and 13 with preeclampsia." (PMID 25148115, 2014). "Placental gene expression of neither CYP24A1 nor CYP27B1 nor VDR differed between seasons or between patients with preeclampsia and healthy controls (as determined by the Mann-Whitney test)." (PMID 25148115, 2014). "mRNA expression of placental CYP24A1, CYP27B1 and VDR (mean ± SD and (range) do not differ between patients with preeclampsia and healthy controls." (PMID 25148115, 2014). "Patients with preeclampsia displayed lower vitamin D serum levels in response to seasonal changes.The regulation of placental CYP24A1, but not of the VDR or CYP27B1 might be altered in preeclampsia." (PMID 25148115, 2014).
viral infections (4 papers, 2021 to 2023). "The potential role of vitamin D in respiratory tract infections is also suggested by the fact that cytochrome P450 family 27 subfamily B member 1 (CYP27B1), which converts vitamin D to its active form, is upregulated by viral infections and is highly expressed in lung epithelial cells." (PMID 33801759, 2021).
benign prostatic hyperplasia (3 papers, 2018 to 2019). A non-cancerous nodular enlargement of the prostate gland. "CYP27B1 expression is significantly reduced in the benign prostatic hyperplasia cells and is reduced further in the cancer-derived cells and cell lines." (PMID 30216977, 2018).
hypogonadism (3 papers, 2015 to 2025). A disorder characterized by decreased function of the gonads. "Cyp27b1 null mice and mice that lack the vitamin D receptor have shown hypogonadism, arrested follicular development, prolonged estrous cycles, and hypoplastic uteri." (PMID 25879830, 2015). "However, even if the correlation between vitamin D and hypogonadism is not entirely clear, it must be considered that the expression of hydroxylases (CYP2R1 and CYP27B1) and VDR in testis tissue also represents a further indication of the importance of the testicles in the metabolism of vitamin D." (PMID 34067977, 2021).
inflammatory bowel disease (3 papers, 2014 to 2025). A spectrum of small and large bowel inflammatory diseases of unknown etiology. "In patients with Crohn's disease as well as in a mouse model of chemically induced inflammatory bowel disease, CYP27B1 expression was enhanced in granulomatous or lymphoid tissue." (PMID 24120915, 2014). "However, in diseases like inflammatory bowel disease (IBD), dysbiosis leads to elevated lipopolysaccharide (LPS) levels and increased cytokine production, disrupting the expression of key vitamin D hydroxylases, including CYP27B1 and CYP24A1." (PMID 41228419, 2025).
leukemia (3 papers, 2018 to 2021). A malignant (clonal) hematologic disorder, involving hematopoietic stem cells and characterized by the presence of primitive or atypical myeloid or lymphoid cells in the bone marrow and the blood. "In future studies, we will examine the anti-leukemia function of CYP27B1+ TILs and also explore whether TILs will be a potential cell vehicle candidate for gene therapies." (PMID 34775232, 2021). "A similar approach has also been demonstrated to be effective in treating leukemia mouse models, by delivering ectopic CYP27B1 to local tissues such as bone marrow cells to compensate the deficiency or incapable generation of CYP27B1 as shown in our recent study." (PMID 32847594, 2020).
Miscarriage (3 papers, 2016 to 2022). A pregnancy that ends at a stage in which the fetus is incapable of surviving on its own, defined as the spontaneous loss of a fetus before the 22th week of pregnancy. "Expressions of CYP27B1 mRNA and protein in villi and decidua from 20 women undergoing primary miscarriage, 20 women with RM and 20 women with normal pregnancy were evaluated by western blot, and quantitative real-time PCR." (PMID 28033387, 2016). "In the present work, we focused only on CYP27B1 level at the fetal-maternal interface in the first trimester pregnancy during women with miscarriage and normal pregnant women." (PMID 28033387, 2016). "The precise molecular mechanisms by which CYP27B1 contributes to decidual and trophoblast functions leading to RM or fetal karyotype has impact on the placental and local target gene responses in the first trimester pregnancy miscarriage warrant further investigation." (PMID 28033387, 2016). "Although it is expected that CYP27B1 level plays an important role in fetal-maternal interface during the first trimester pregnancy, the impact of the fetal karyotype on CYP27B1 gene activity in the first trimester pregnancy miscarriage is not known." (PMID 28033387, 2016).
psoriasis (3 papers, 2016 to 2023). An autoimmune condition characterized by red, well-delineated plaques with silvery scales that are usually on the extensor surfaces and scalp. "Compared with healthy skin, in psoriasis, it is reported that the enzyme’s expression seems to be more ubiquitous, but a clear correlation between the disease’s severity and the CYP27B1 expression was, to our knowledge, lacking." (PMID 38276264, 2023). "In spite of that, the staining CYP27B1 assessment could be significantly correlated with none of the psoriasis scores (p = 0.493 for the PASI score and p = 0.672 for the DLQI score)." (PMID 38276264, 2023). "None of our psoriasis patients had strong CYP27B1 enzyme staining." (PMID 38276264, 2023). "The CYP27B1 enzyme was absent in the sample of three of our patients with moderate to severe psoriasis and we highlight the importance of finding if this could be predictive of a poorer prognosis of the disease." (PMID 38276264, 2023). "Unlike malignant diseases, a significant connection between CYP27B1 and Ki67 (p = 0.313) or CYP27B1 and CD45RO+ (p = 0.657) does not seem to be relevant in psoriasis." (PMID 38276264, 2023).
pulmonary fibrosis (3 papers, 2019 to 2022). Chronic progressive interstitial lung disorder characterized by the replacement of the lung tissue by connective tissue, leading to progressive dyspnea, respiratory failure, or right heart failure. "In the present study, we observed the effects of active vitamin D3 deficiency on BLM-evoked EMT and pulmonary fibrosis using a model of Cyp27b1 gene knockout mice." (PMID 31775746, 2019). "Additional experiment showed that Cyp27b1 gene knockout, leading to active vitamin D3 deficiency, exacerbated BLM-induced pulmonary fibrosis." (PMID 31775746, 2019). "We found that Cyp27b1 gene knockout, leading to active vitamin D3 deficiency, exacerbated BLM-induced pulmonary fibrosis." (PMID 31775746, 2019). "Our results indicated that both feeding VDD diet and Cyp27b1 gene knockout exacerbated BLM-induced pulmonary fibrosis." (PMID 31775746, 2019). "Of interest, Cyp27b1 knockout aggravated collagen deposition, as accessed by Sirius red staining, in BLM-induced pulmonary fibrosis." (PMID 31775746, 2019). "Interestingly, genes related to vitamin D regulation (CYP27B1), inflammation (IRAK3) and pulmonary fibrosis (MMP1) were significantly induced by both viruses." (PMID 33301474, 2020). "Moreover, Cyp27b1 gene knockout aggravated pulmonary TGF-β/Smad2/3 activation and subsequent EMT in BLM-induced lung fibrosis." (PMID 31775746, 2019). "In addition, Cyp27b1 gene knockout aggravated pulmonary TGF-β/Smad2/3 activation and subsequent EMT during BLM-induced lung fibrosis." (PMID 31775746, 2019).
thyroid cancer (3 papers, 2015 to 2023). "The low level of vitamin D was initially associated with an increased risk of thyroid cancer development, however CYP27B1 expression is increased in the case of thyroid nodular cancer." (PMID 32197412, 2020). "It was characterized by the increased levels of VDR, CYP24A1 and CYP27B1 in benign and differentiated malignant thyroid tumors." (PMID 25501638, 2015). "The thyroid is another CYP27B1 expression site; however, no polymorphism within CYP27B1 has been studied for any type of thyroid cancer." (PMID 32197412, 2020).
vitamin D-dependent rickets (3 papers, 2020 to 2023). "There was no improvement initially, hence the siblings were reinvestigated and later diagnosed as having vitamin D-dependent rickets (VDDR) type 1 due to a rare mutation in the CYP27B1 gene encoding the 1α-hydroxylase enzyme." (PMID 32926064, 2020).
vitamin D-dependent rickets, type 1 (3 papers, 2014 to 2024). Hypocalcemic vitamin D-dependent rickets (VDDR-I) is an early-onset hereditary vitamin D metabolism disorder characterized by severe hypocalcemia leading to osteomalacia and rachitic bone deformations, and moderate hypophosphatemia. "Mutations in CYP27B1 lead to 1α-hydroxylase deficiency, known as vitamin D-dependent rickets type 1 or hereditary pseudo-vitamin D-deficient rickets, while mutations in CYP2R1 result in 25-hydroxylase deficiency." (PMID 38892599, 2024). "Different types of mutations within the CYP27B1 gene, such as sense-change mutations, insertions, and deletions, lead to rats associated with vitamin-D-dependent rickets type 1, which is a rare autosomal recessive disease." (PMID 32197412, 2020). "Vitamin D dependent rickets type 1 is inherited in an autosomal recessive pattern, and is caused by mutations in the CYP27B1 gene encoding the 1α-hydroxylase enzyme." (PMID 25371233, 2014). "We report here a new mutation in CYP27B1, which lead to Vitamin D dependent rickets type 1." (PMID 25371233, 2014).
Autoimmune Addison's disease (2 papers, 2014 to 2022). "CYP27B1 promoter allele is associated with autoimmune Addison’s disease, and extend this finding to include an associated promoter haplotype." (PMID 36313775, 2022).
bladder cancer (2 papers, 2015 to 2019). "In the future we plan to perform prospective study on vitamin D serum level, VDR polymorphisms and epigenetic regulation of VDR and CYP27B1 expression in in patients with bladder cancer." (PMID 26501255, 2015). "We analyzed VDR and CYP27B1 in samples of tumor and normal tissues obtained from 71 urinary bladder cancer patients." (PMID 26501255, 2015). "However, our analysis of VDR and CYP27B1 immunostaining in urinary bladder cancers is very comprehensive and clinically significant, because of inclusion of data on overall survival time, which also correlated with histological parameters." (PMID 26501255, 2015). "The aim of the present research was to examine whether the expression of the VDR and CYP27B1 in bladder cancer was related to the prognostic markers and disease outcome." (PMID 26501255, 2015). "Summary of the results related to VDR and CYP27B1 expression in urinary bladder cancers." (PMID 26501255, 2015). "The expression of both the VDR and CYP27B1 has been found in many normal and cancer tissues, but there is a lack of information about its expression in human bladder cancers." (PMID 26501255, 2015). "There was a strong relationship between VDR expression and the biology and stage of bladder cancers, with a lack of such correlation for CYP27B1." (PMID 26501255, 2015). "However, CYP27B1 expression in bladder cancer did not correlate with pT stage, presence of metastasis, tumor grade, mitotic activity, and OS (not shown)." (PMID 26501255, 2015).
kidney failure (2 papers, 2015 to 2021). An acute or chronic condition that is characterized by the inability of the kidneys to adequately filter the blood. "Despite elevated blood FGF23, both kidney failure models augmented renal Cyp27b1 expression, probably due to the observed increase in PTH." (PMID 26566277, 2015).
leprosy (2 papers, 2018 to 2023). Leprosy is a chronic infectious disease affecting primarily the skin and peripheral nervous system. "In addition, IL18RAP and CYP27B1 were pinpointed as causal genes through colocalized the leprosy‐associated signals with eQTL signals of skin and nerve." (PMID 38020709, 2023). "Linear regression analysis indicates that CD163 and OAS1 expression are coordinately expressed (P = 0.0004, R2 = 0.6019) and two way ANOVA analysis confirms that leprosy type of the lesion is significantly (P = 0.0003) associated with differential gene expression of CYP27B1, CD163 and OAS1." (PMID 30300363, 2018). "Quantification of protein expression levels in the leprosy lesions indicated that there were 3-fold higher number of CYP27B1 positive cells in the T-lep vs. L-lep lesions." (PMID 30300363, 2018). "Examining the distribution of CYP27B1 protein in leprosy lesions by immunohistochemistry, we observed greater expression of the enzyme throughout the granulomas in the T-lep vs. L-lep form, correlating with mRNA levels." (PMID 30300363, 2018). "This suppression of CYP27B1 has in vivo relevance, as we found that CYP27B1 is more highly expressed in T-lep vs. L-lep lesions, the self-limited vs. progressive forms of leprosy, respectively, and was inversely correlated with type I IFN signaling." (PMID 30300363, 2018). "Consistent with these in vitro studies, an inverse relationship between expression of CYP27B1 vs. type I IFN downstream gene OAS1 was detected in leprosy patient lesions, leading us to study cytokine-derived macrophages (MΦ) to model cellular responses at the site of disease." (PMID 30300363, 2018).
metastatic tumors (2 papers, 2015 to 2020). "In 3 pairs, there were no changes in CYP27B1 expression in metastases vs. the primary lesions, in 5 cases a lower CYP27B1 level was observed in the metastatic tumors, and in 5 cases lower CYP27B1 immunostaining was recorded in the primary cancers." (PMID 25501638, 2015).
non-Hodgkin lymphoma (2 papers, 2014 to 2020). Distinct from Hodgkin lymphoma both morphologically and biologically, non-Hodgkin lymphoma (NHL) is characterized by the absence of Reed-Sternberg cells, can occur at any age, and usually presents as a localized or generalized lymphadenopathy associated with fever and weight loss. "Two out of four non-Hodgkin's lymphoma cell lines showed strong methylation of the CYP27B1 promoter." (PMID 24808866, 2014). "The CYP27B1 promoter was hypermethylated (61%) in Non-Hodgkin's lymphoma, but not in benign follicular hyperplasia." (PMID 24808866, 2014).
oral cancer (2 papers, 2023). "Moreover, excessive alcohol consumption has been associated with VDR CYP27B1 polymorphism, which is correlated with an increased risk for oral cancer." (PMID 37242229, 2023).
oral lichen planus (2 papers, 2020). Oral lichen planus is a chronic inflammatory oral condition of unknown aetiology characterized by T-cell-mediated chronic immune response and abnormal epithelial keratinization cycle. "Correlation of MTHFR gene, CYP27b1, and cyp24a1, with the risk of developing oral lichen planus." (PMID 33527053, 2020).
osteomalacia (2 papers, 2017 to 2020). Disorder caused by an interruption of the mineralization of organic bone matrix leading to bone softening, bone pain, and weakness. "In addition, increased unmineralized osteoid, which is the hallmark of osteomalacia, was observed in Cyp27b1-KO rats and Vdr (R270L) rats but not in Vdr-KO rats at 15 weeks of age." (PMID 32231239, 2020).
ovarian tumor (2 papers, 2015 to 2023). "In summary, our results suggest that local expression of CYP27B1 in ovarian tumor cells can modify their behavior and promote a less aggressive phenotype by affecting local concentrations of active of vitamin D levels within the tumor microenvironment." (PMID 25501638, 2015). "A similar relationship with reference to CYP27B1 mRNA levels was found in ovarian tumor cell lines." (PMID 25501638, 2015). "The expression of CYP27B1 was observed in 49 (80.3%) cases of primary ovarian tumors." (PMID 25501638, 2015). "Expression of CYP27B1 was evaluated in 61 ovarian tumors, 18 metastases and 10 normal ovaries." (PMID 25501638, 2015).
periodontitis (2 papers, 2012 to 2021). An acute or chronic inflammatory process that affects the tissues that surround and support the teeth. "Although the actual situation in vivo is much more complex than that simulated in the laboratory, our observations that patients with periodontitis had higher mRNA expression of CYP27B1 and higher CYP27B1 staining scores were in line with our results in vitro." (PMID 33505780, 2021). "In the periodontitis group, the expression of CYP27B1 was detected in all epithelial layers, but expression was stronger in the superficial layer than in the deep layer of the epithelia in the control group." (PMID 33505780, 2021). "In all the 40 × microscopic fields chosen for analysis, almost 100% of the hGFs were CYP27B1 positive and the CYP27B1 staining scores of hGFs of patients with periodontitis (2.49 ±0.08) were significantly higher than those of controls (1.84 ±0.12)." (PMID 33505780, 2021). "The mRNA expressions of CYP27B1 in gingival connective tissues of patients with periodontitis were significantly higher than those in the gingival connective tissues of controls." (PMID 33505780, 2021). "Statistical analysis indicated that CYP27B1 staining intensities of the gingiva of patients with periodontitis [3.00, (3.00 to 3.00)] were significantly higher than those of the controls [1.00, (1.00 to 2.00)]." (PMID 33505780, 2021). "In the present study, the finding that the in vivo gingival CYP27B1 expression was higher in the periodontitis group than in the control group could provide new evidence of the involvement of the vitamin D pathway in periodontal immune defense." (PMID 33505780, 2021). "Thus, based on our previous data, it might be hypothesized that CYP27B1 is expressed in hGFs in vivo and patients with periodontitis might have stronger expression." (PMID 33505780, 2021). "Previously, our group reported that IL-1β and butyric acid, which are both up-regulators of CYP27B1, could be detected in the gingival crevicular fluids of patients with periodontitis, and the concentrations were positively correlated with periodontal inflammation." (PMID 33505780, 2021). "However, although stimuli with periodontal characteristics were used here to simulate a periodontitis condition, this does not properly model a chronic disease situation in vivo and can only help to investigate the regulation of CYP27B1 in hGF and hPDLC." (PMID 22761920, 2012).